ABCE1 (ATP binding cassette subfamily E member 1)
Description:
Nucleoside-triphosphatase (NTPase) involved in ribosome recycling by mediating ribosome disassembly. Able to hydrolyze ATP, GTP, UTP and CTP. Splits ribosomes into free 60S subunits and tRNA- and mRNA-bound 40S subunits. Acts either after canonical termination facilitated by release factors (ETF1/eRF1) or after recognition of stalled and vacant ribosomes by mRNA surveillance factors (PELO/Pelota). Involved in the No-Go Decay (NGD) pathway: recruited to stalled ribosomes by the Pelota-HBS1L complex, and drives the disassembly of stalled ribosomes, followed by degradation of damaged mRNAs as part of the NGD pathway. Also plays a role in quality control of translation of mitochondrial outer membrane-localized mRNA. As part of the PINK1-regulated signaling, ubiquitinated by CNOT4 upon mitochondria damage; this modification generates polyubiquitin signals that recruit autophagy receptors to the mitochondrial outer membrane and initiate mitophagy. RNASEL-specific protein inhibitor which antagonizes the binding of 2-5A (5'-phosphorylated 2',5'-linked oligoadenylates) to RNASEL. Negative regulator of the anti-viral effect of the interferon-regulated 2-5A/RNASEL pathway. (Microbial infection) May act as a chaperone for post-translational events during HIV-1 capsid assembly. (Microbial infection) Plays a role in the down-regulation of the 2-5A/RNASEL pathway during encephalomyocarditis virus (EMCV) and HIV-1 infections.
Synonyms: RNS4I; RLI; RNASEL1; RNASELI; OABP; RLI1; ABC38
Tractability: Small molecule: a structure with a bound ligand is known. PROTAC: UniProt records ubiquitination sites on it; ubiquitination databases record sites on it; its protein half-life has been measured.
Target class: Enzyme; Hydrolase
Gene: Protein-coding gene on chromosome 4 (145,098,248 to 145,129,524, forward strand). Ensembl gene ENSG00000164163.
Subcellular location: Cytoplasm; Mitochondrion
Subcellular location (Human Protein Atlas): Cytosol
Pathways (Reactome):
Immune System: Interferon alpha/beta signaling; OAS antiviral response
Metabolism of proteins: PELO:HBS1L and ABCE1 dissociate a ribosome on a non-stop mRNA
Gene Ontology:
Molecular function: ATP hydrolysis activity; CTPase activity; endoribonuclease inhibitor activity; GTPase activity; protein binding; ribonucleoside triphosphate phosphatase activity; ATP binding; iron ion binding; ribosomal small subunit binding
Biological process: negative regulation of endoribonuclease activity; rescue of stalled ribosome; ribosome disassembly; translational termination; translational initiation; translation
Cellular component: cytoplasm; cytosol; cytosolic ribosome; membrane; mitochondrion; mitochondrial matrix
Genetic constraint (gnomAD): Loss-of-function variants: 15 observed, 49.61 expected, observed/expected ratio (o/e) 0.3, 90% interval 0.2 to 0.47. The upper end of that interval is the gene's LOEUF score, 0.47, which puts it in group 2 of 6, group 1 being the genes least tolerant of losing a copy. Missense variants: 258 observed, 569.14 expected, observed/expected ratio (o/e) 0.45, 90% interval 0.41 to 0.5. Synonymous variants: 172 observed, 190.19 expected, observed/expected ratio (o/e) 0.9, 90% interval 0.8 to 1.03.
Homologues: Orthologues: chimpanzee ABCE1 (100% identical), guinea pig ABCE1 (100% identical), macaque ABCE1 (100% identical), mouse Abce1 (100% identical), dog ABCE1 (98% identical), pig ABCE1 (98% identical), rat Abce1 (93% identical), zebrafish abce1 (90% identical), tropical clawed frog abce1 (89% identical), Drosophila melanogaster pix (77% identical), Caenorhabditis elegans abce-1 (67% identical).
Diseases named in the same sentence as ABCE1 in open-access papers:
ABCE1 is named in the same sentence as 33 diseases in open-access papers, as found by Europe PMC text mining. Sharing a sentence is not in itself a finding about the gene and the disease. The quoted sentences say what the papers report.
lung carcinoma (12 papers, 2012 to 2026). "In lung cancer ABCE1 overexpression is milder and is associated with poor survival." (PMID 41663214, 2026). "For instance, the Abce1 gene has been associated with promotion of cell proliferation, migration and invasion, as well as decreased apoptosis in several types of tumors, including lung cancer and oral squamous cell carcinoma." (PMID 36361810, 2022). "Previous research has shown that ABCE1 plays an essential role in lung cancer progression and metastasis." (PMID 33902514, 2021). "Gene silence of Tip60 in lung cancer cells by designed siRNA reduces the acetylation of ABCE1, accompanied by reduced tumor weight and volume." (PMID 33287240, 2020). "ABCE1 (ATP-binding cassette E1) plays a crucial role in the metastasis and progress of lung cancers, and therefore it has been suggested as a valuable therapeutic target for the management of these cancers." (PMID 27419373, 2016). "Studies in lung cancer have shown that overexpression of ABCE1 in tumor cells promotes growth and inhibits apoptosis." (PMID 25070080, 2014). "Furthermore, acetylation of ATP-binding cassette transporter E1 (ABCE1), which is often induced by a Tat interactive protein 60 kDa (Tip60), has been found to be increased in the tissues and cells of lung cancer." (PMID 33287240, 2020). "ABCE1 is the target gene of miR-299-3p in lung cancer cells." (PMID 32513149, 2020). "Furthermore, ABCE1 has been found to be involved in the occurrence and development of lung cancer, and RNase L has been shown to affect the pathogenesis of prostate cancer." (PMID 25070080, 2014). "ABCE1 mRNA and protein were differentially expressed in lung cancers of different clinical stages." (PMID 22267055, 2012). "Relying on patient transcriptomic data, we show that ABCE1 is extensively overexpressed in colorectal cancer (CRC) and to a lesser extent in lung cancer." (PMID 41663214, 2026).
breast carcinoma (7 papers, 2014 to 2024). "Collectively, these data indicate that enforced TET2 activity in MCF-7 breast cancer cells triggers a pre-activated antiviral state that predisposes cells to death induced by ABCE1 inactivation." (PMID 35351824, 2022). "The present study revealed that the treatment of human breast cancer cells with ABCE1-siRNA caused morphological and biochemical changes." (PMID 25070080, 2014). "The knockdown of ABCE1 expression in human esophageal cancer, breast cancer, and small cell lung cancer cells causes reduced proliferation, increased apoptosis, migration, and invasion; however, the role of RNase L inhibition in mediating these effects remains to be determined." (PMID 33670646, 2021). "To test whether ABCE1 acts alone or in concert with other miR-96 target genes, we referred to our previously published list of twelve breast cancer-associated genes predicted to be regulated by miR-96." (PMID 31007850, 2019). "Knockdown of ABCE1 inhibits proliferation and migration and induces apoptosis in small cell lung cancer, breast cancer, and esophageal cancer cells." (PMID 33670646, 2021). "We demonstrated that downregulation of LCP1 resulted in significantly reduced breast cancer cell migration and invasion, and that dual ABCE1+LCP1 knockdown further inhibits cell motility, especially invasion." (PMID 31007850, 2019). "We previously demonstrated that miR-96 has a suppressive effect on breast cancer aggressiveness and that this effect was mediated by ABCE1 gene regulation." (PMID 31007850, 2019). "In this study, we showed that ABCE1 is downregulated in human and mouse breast cancer cell lines, both on the RNA and protein levels, in response to miR-96 overexpression." (PMID 30305609, 2018). "Clinical and gene expression data from human breast cancer patients further corroborated the roles of miR-96 and ABCE1 in tumor aggressiveness." (PMID 30305609, 2018). "We identified ABCE1 as a direct target of miR-96 and validated the suppressive effect of miR-96 and ABCE1 on breast cancer cell migration, invasion, and proliferation." (PMID 30305609, 2018). "Utilizing the Human Protein Atlas42, we noted that ABCE1 was the only candidate with moderate to strong IHC expression profile in breast cancer tissues." (PMID 30305609, 2018). "We demonstrated that both overexpression of miR-96 and downregulation of ABCE1 result in significantly reduced breast cancer cell migration and invasion in 2D culture, and to even greater extent in 3D culture." (PMID 30305609, 2018). "ABCE1 was observed to be overexpressed in breast cancer tissue compared with adjacent normal breast tissue." (PMID 25070080, 2014). "In the present study, ABCE1 expression was assessed in breast cancer tissue and adjacent normal breast tissue using immunohistochemistry." (PMID 25070080, 2014). "In order to investigate the role of ABCE1 in breast cancer, ABCE1 expression was analyzed in breast cancer tissue compared with adjacent healthy breast tissue." (PMID 25070080, 2014). "Breast cancer is the most common type of cancer among females and the adenosine triphosphate (ATP) binding cassette E1 (ABCE1) gene is a member of the ATP-binding cassette (ABC) family." (PMID 25070080, 2014). "In the present study, ABCE1 protein was observed to be significantly overexpressed in breast cancer tissue compared with adjacent normal breast tissue (P<0.01)." (PMID 25070080, 2014). "In the present study, RNA interference (RNAi) was used to knock down ABCE1 expression in MCF-7 human breast cancer cells to investigate the role and mechanism of ABCE1 in breast cancer progression." (PMID 25070080, 2014). "However, little is known about whether the ABCE1 gene is associated with breast cancer." (PMID 25070080, 2014). "The present study identified that ABCE1 was highly expressed in breast cancer and that breast cancer malignancy was correlated with ABCE1 expression." (PMID 25070080, 2014).
breast carcinoma (continued). "In the present study, a decrease in ABCE1 expression and an increase in RNase L expression was observed in breast cancer." (PMID 25070080, 2014). "Downregulation of ABCE1 was found to inhibit proliferation and invasion in breast cancer cells." (PMID 30305609, 2018). "Finally, by comparing human clinical data and survival with tumor RNA expression, we showed that miR-96 and ABCE1 have a significant role in breast cancer progression." (PMID 30305609, 2018). "Specifically in our study, breast cancer aggressiveness was dictated by miR-96 regulating ABCE1." (PMID 30305609, 2018). "Human data analysis further strengthened miR-96/ABCE1 role in breast cancer tumor aggression." (PMID 30305609, 2018). "In conclusion, the present study provided an enhanced understanding of the physiological role of ABCE1 in breast cancer and may provide novel insight for the development of gene therapy technology to treat patients with breast cancer." (PMID 25070080, 2014). "Furthermore, small interfering (si)RNA targeting ABCE1 was constructed and transfected into MCF-7 human breast cancer cells to downregulate ABCE1 expression." (PMID 25070080, 2014). "This may be one of the mechanisms through which ABCE1 affects breast cancer proliferation, invasion and apoptosis." (PMID 25070080, 2014). "However, the role of ABCE1 in metastasis and proliferation in breast cancer has yet to be elucidated." (PMID 25070080, 2014). "ABCE1-RNAi was found to induce morphological changes in MCF-7 human breast cancer cells." (PMID 25070080, 2014). "Furthermore, ABCE1 expression was found to be significantly higher in the breast cancer tissue compared with the adjacent healthy breast tissue (P<0.01), suggesting that ABCE1 may have a role in breast cancer." (PMID 25070080, 2014). "This suggested that ABCE1 may be involved in the occurrence and development of breast cancer." (PMID 25070080, 2014). "Together, these results suggest that the additive effect of two miR-96 gene targets, ABCE1 and LCP1, has a functional role in the downregulation of breast cancer growth, aggressiveness, and survival." (PMID 31007850, 2019). "To examine the effect of LCP1 knock down (KD) and dual ABCE1+ LCP1 KD on cell migration, we used shRNAs to stably underexpress ABCE1, LCP1, ABCE1+ LCP1, or scrambled in HS578 human breast cancer cells and 4T1 murine breast carcinoma cells." (PMID 31007850, 2019). "Furthermore, using bioinformatics analysis, biological validation experiments, and human breast cancer data we identified miR-96 as an active metastasis suppressor gene and demonstrated that its ability to reduce metastatic activity depends on its regulation of ABCE1." (PMID 30305609, 2018). "To evaluate ABCE1 as a miR-96 target in vitro and in vivo, we examined its expression in 4T1, MDA-231, and HS578 breast cancer cells that overexpress miR-96 or scrambled miRNA." (PMID 30305609, 2018). "In order to investigate the role of ABCE1 in breast cancer, siRNA knockdown of the ABCE1 gene was performed in the MCF-7 breast cancer cell line." (PMID 25070080, 2014). "However, when looking at the correlation between TET2 expression and antiviral response genes in breast cancer patients, a positive correlation was found only for EIF2AK2, MAVS, OTUD4, ABCE1, and RNase L expression levels." (PMID 35351824, 2022). "Therefore, we proceeded to explore the role of LCP1 in breast cancer metastasis formation and, especially, the additive effect of LCP1 and ABCE1 on this process." (PMID 31007850, 2019).
viral infection (7 papers, 2013 to 2022). "Downregulation of ABCE1, one of the encoded proteins identified in our study, concurs with the presence of previous viral infections, as the protein inhibits RNase L’s viral RNA degrading activity." (PMID 33633136, 2021). "ATP-binding cassette E1 (ABCE1) transporter, identified as an inhibitor of RNase L, regulates RNase L activity and RNase L-induced autophagy during viral infections." (PMID 36284352, 2022). "Here, we show that the ATP-binding cassette E1 (ABCE1) transporter, identified as an inhibitor of RNase L, regulates RNase L activity and RNase L-induced autophagy during viral infections." (PMID 33670646, 2021). "ABCE1 is a member of the ATP-binding cassette transporter family and regulates a broad range of biological functions including viral infection, cell proliferation, and anti-apoptosis." (PMID 33902514, 2021). "ABCE1 functions in translation initiation, ribosome biogenesis, cell proliferation, viral infection, anti-apoptosis and human immunodeficiency virus capsid assembly." (PMID 28380459, 2017). "ABCE-1 was also shown to inhibit the antiviral activity of interferon in humans, and hence to modulate innate immune response against viral infections including HIV." (PMID 23324493, 2013). "Further ABCE1 role has been detailed during viral infection and anti-apoptosis in humans." (PMID 34578158, 2021). "ATP-binding cassette E1 (ABCE1) is a member of the ATP-binding cassette transporters and essential for diverse biological events regulating abroad range of biological functions including viral infection, cell proliferation, anti-apoptosis, translation initiation and ribosome biogenesis." (PMID 28380459, 2017). "Our studies identify ABCE1 as a regulator of the OAS/RNase L pathway by balancing and fine-tuning the RNase L activity that can impact the outcomes of viral infections." (PMID 33670646, 2021). "In these studies, ABCE1 was transcriptionally induced by virus infection and not IFN." (PMID 33670646, 2021).
colorectal cancer (3 papers, 2016 to 2026). A primary or metastatic malignant neoplasm that affects the colon or rectum. "In the Human Protein Atlas database, ABCE1 protein is expressed at similar levels in colorectal cancer tissues as well as in normal tissues, which agrees with our data." (PMID 34440115, 2021). "Here, we show that the uORFs present in the 5′-leader sequence of the human ABCE1 transcript are able to efficiently repress translation of the main coding sequence in HCT116 colorectal cancer cells." (PMID 34440115, 2021). "Ribosome profiling analysis in colorectal cancer cells has revealed a high ribosome occupancy in the human ABCE1 mRNA 5′-leader sequence, indicating the presence of translatable upstream open reading frames (uORFs)." (PMID 34440115, 2021). "In a contradicting study by Hlavata and co-workers, an upregulation of ABCE1 mRNA in a pool of colorectal cancers was shown." (PMID 34440115, 2021). "Conversely, Hlavata and co-workers reported an upregulation of ABCE1 mRNA in a pool of colorectal cancers." (PMID 34440115, 2021). "Taking into account the important functions of the ABCE1 protein and the unknown role of its uORFs, our aim was to study the function of ABCE1 uORFs in its translational control in colorectal cancer cells." (PMID 34440115, 2021). "Nevertheless, when we look at these uORFs together in their native configuration, we observe that the complex uORF architecture in the 5′-leader sequence of the ABCE1 mRNA is able to significantly repress expression of the downstream main coding sequence in about 70% in colorectal cancer cells." (PMID 34440115, 2021). "Our results show that in the human colorectal carcinoma cell line HCT116, translation of the ABCE1 mRNA is regulated by the AUG uORFs within its 5′-leader sequence." (PMID 34440115, 2021). "To address these questions, we studied the translational regulation mediated by the AUG uORFs of the ABCE1 transcript in a non-tumorigenic versus colorectal cancer cell line." (PMID 34440115, 2021). "Supporting the lack of oncogenic function of the ABCE1 AUG uORFs, both ABCE1 mRNA and protein levels are similar in different colorectal cancer cell lines, as well as in the non-tumorigenic NCM460 cells." (PMID 34440115, 2021). "Respectively, the ABCE1 mRNA and protein levels are maintained unaffected in all the colorectal cancer cell lines tested and are at levels comparable to those in NCM460 cells, supporting the absence of a link between ABCE1 uORF-mediated translational control and cancer progression." (PMID 34440115, 2021).
esophageal cancer (3 papers, 2015 to 2021). A primary or metastatic malignant neoplasm involving the esophagus. "In order to examine the effect of ABCE1 on the migration of esophageal cancer cells in the present study, the gene expression of ABCE1 in EC109 esophageal cancer cells was inhibited by electroporation." (PMID 25815591, 2015). "Specific interference of the gene expression of ABCE1 can inhibit the migration of EC109 esophageal cancer cells and tumor cell proliferation." (PMID 25815591, 2015). "In the present study, the gene expression of ATP-binding cassette protein E1 (ABCE1) in the EC109 human esophageal cancer cell line was silenced using electroporation to examine the effect if the ABCE1 gene on the growth migration and cell cycle of cancer cells." (PMID 25815591, 2015). "The effect of silencing the ABCE1 gene on the proliferation, migration and invasive ability of the EC109 human esophageal cancer cells were assessed using a Cell counting kit-8 (CCK-8) and with proliferation, wound-healing and cell invasion assays." (PMID 25815591, 2015). "Therefore, the ABCE1 siRNA sequence may be an effective target site for esophageal cancer therapy and the inhibition of ABCE1 by electroporation may offer a novel therapeutic method in the treatment of malignant tumors, including esophageal cancer." (PMID 25815591, 2015).